EGFR (epidermal growth factor receptor)
Diseases named in the same sentence as EGFR in open-access papers (continued):
Sharing a sentence is not in itself a finding about the gene and the disease.
lung cancer (continued). "The aim of this study is to determine whether the clinical features including blood markers can establish an explainable machine learning model to predict epidermal growth factor receptor (EGFR) mutation in lung cancer." (PMID 35814445, 2022). "Targeted drugs combined with antiangiogenic agents may be an effective new option for lung cancer patients with EGFR mutations." (PMID 34855286, 2022). "One of the major genetic causes of lung cancer is EGFR activity." (PMID 36054194, 2022). "A study using the MarketScan database analyzed utilization patterns in testing for EGFR mutations from 2013 to 2014; however, it did not include histology information and therefore was unable to exclude patients with lung cancer histologies with lower rate of EGFR mutations." (PMID 35397521, 2022). "However, although EGFR mutations provide a promising biomarker for patients with lung cancer treated with EGFR-tyrosine kinase inhibitors (TKIs), around 20% of patients with EGFR mutations fail to respond to these agents." (PMID 36253772, 2022). "We first evaluated whether the mechanism of acquired EGFR-TKI resistance varies among individual tumors using two lung cancer cell lines harboring the same EGFR mutation." (PMID 35326664, 2022). "However, we found a rare mutation of EGFR Ex19del/G724S in two patients with lung cancer who demonstrated a favorable response to the combination of afatinib and chemotherapy." (PMID 36505860, 2022). "The researchers are in general agreement that the main influential factors contributing to the differences in EGFR gene mutation of the lung cancer patients in Eastern Yunnan were at least in part generated from the human-induced environmental pollution during the process of mining." (PMID 35606799, 2022). "Recent advances in cancer biology and genomics research have allowed an in-depth characterization of lung cancers that have revealed new therapy targets (EGFR, ALK, ROS, and KRAS mutations) and have the potential of revealing even more biomarkers for diagnostic, prognostic, and targeted therapies." (PMID 35628157, 2022). "Consistent with these clinical data, other investigators observed early clinical progression associated with decreased sensitivity to EGFR TKI therapy in a patient with EGFRL858R lung cancer whose tumor also harbored a clonal co-occurring truncating RBM10 mutation." (PMID 35579943, 2022). "Mutations in EGFR have been implicated in lung cancer pathogenesis." (PMID 35813479, 2022). "Except the EGFR, the long non-coding RNA H19 causes the progression and metastasis of lung cancer, and the LAMC1 SNP rs3768617 could also increase the risk of lung cancer." (PMID 36011604, 2022). "NEK2 was reported to be elevated in lung cancer, regulated by EGFR mutation." (PMID 35311097, 2022). "Currently, EGFR inhibitors are the first-line drugs for curing lung cancer with EGFR mutation." (PMID 35935840, 2022). "The author also explained that the lower risk of SPMs among patients with lung cancer treated with TKIs may be related to the downregulation of EGFR activity." (PMID 36079152, 2022). "Resistance to the anti-EGFR antibody cetuximab in lung cancer is also associated with deregulation of EGFR internalization/degradation and may be associated to activation of HER3." (PMID 36271429, 2022). "EGFR-mutated (n = 23) relative to wild-type (n = 93) lung cancers showed an up-regulation of the feature “kurtosis” (median: 3.87 vs 2.48; p = 0.0238), and down-regulation of the features “maximum-probability” (0.53 vs 0.75; p = 0.0130) and “energy” (0.05 vs 0.09; p = 0.0401)." (PMID 35482262, 2022). "EGFR-TKI is the standard first-line treatment for EGFR-mutated lung cancer patients." (PMID 36528578, 2022).
lung cancer (continued). "In this sense, EGFR represents the most frequently mutated driver gene in lung cancer." (PMID 35565304, 2022). "Furthermore, two randomized phase II clinical trials were conducted to compare afatinib and platinum-doublet chemotherapy in patients with advanced lung carcinoma harboring mutated EGFR." (PMID 35164092, 2022). "EGFR mutation prevalence can also vary depending on smoking status, sex, and lung cancer histology." (PMID 34202748, 2021). "In the field of target therapy for lung cancer, epidermal growth factor receptor (EGFR) T790M mutation gradually emerges with the initial mutation of 19del or L858R unchanged, thus leading to AR to the first- or second-generation tyrosine kinase inhibitors (TKIs)." (PMID 34194441, 2021). "Moreover, FGFR3 was also found as one of the fusion proteins that cause acquired resistance to EGFR inhibitors in lung cancer patients." (PMID 34830951, 2021). "Apoptotic response is the final step when EGFR-mutated lung cancer cells are killed by an EGFR-TKI." (PMID 33572269, 2021). "EGFR mutant lung cancer cells were shown to be more dependent on cholesterol for proliferation compared to EGFR wild-type cancer cells; it could be speculated that EGFR mutation plays a role between lipid metabolism and lung cancer carcinogenesis." (PMID 33924149, 2021). "In addition, ASO-1316 reduced tumorigenicity of KRAS/EGFR mutated lung cancer cell lines in orthotopic mice models." (PMID 33740988, 2021). "At the time of development of EGFR TKIs, it was unknown that some lung cancers bore activating mutations in EGFR." (PMID 34202748, 2021). "In the WJOG8815L phase II clinical study, we monitored EGFR mutation fractions (MFs) in the circulating tumor DNA (ctDNA) of EGFR T790M mutation‐positive patients with non‐small cell lung cancer (NSCLC) that received treatment with the tyrosine kinase inhibitor (TKI) osimertinib." (PMID 33131198, 2021). "Similarly, sensitivity to the epidermal growth factor receptor (EGFR) tyrosine kinase inhibitor drug Erlotinib correlated with EGFR-mutations in lung cancer-derived organoids." (PMID 33801782, 2021). "Thus, EGFR-TKI resistance can evolve in EGFR-mutated lung cancer cells via COLI uptake mediated by micropinocytosis." (PMID 34976811, 2021). "Small molecule inhibitors for the treatment of signal kinases will cause changes in drug targets, for example, certain lung cancer patients with EGFR mutations developed resistance to EGFR inhibitors within one year, and EGFR-T790M gatekeeper mutation was reported in half of the cases." (PMID 34568317, 2021). "Detection of the mutation of the EGFR gene is beneficial for the early diagnosis of lung cancer." (PMID 34577205, 2021). "Moreover, many studies have described the genetic susceptibility to develop lung cancer especially in North Africa by identifying genetic biomarkers in EGFR, KRAS and ALK genes." (PMID 33937056, 2021). "Several studies have addressed the correlation between mutations and semiquantitative parameters of nuclear medicine imaging and the most relevant example is to predict EGFR mutation in lung cancer by 18F-fluorodeoxyglucose (FDG) positron emission tomography (PET)." (PMID 33995277, 2021). "In addition, EGFR‐mutated lung cancer has been previously shown to have a lower TMB compared with EGFR wild‐type lung cancer." (PMID 33210451, 2021). "EGFR mutations result in the activation of EGFR and its downstream signaling pathways, which contribute to the progression of many human cancers, including lung cancer." (PMID 35126111, 2021). "In accordance with the hypothesis, we observed that SIRT7 overexpression suppressed the growth of xenografted H1975 lung cancer cells, which possess the constitutively activated EGFR L858R/T790M mutation." (PMID 34433808, 2021). "For example, in lung cancer, the genotype of epidermal growth factor receptor (EGFR) guides the use of treatment with multiple tyrosine-kinase inhibitors targeted to the mutated EGFR protein." (PMID 34441338, 2021).
lung cancer (continued). "Furthermore, a combination of ANF and a TKI such as GEF synergistically inhibited the growth of lung cancer cells harboring specific mutations in EGFR that confer chemoresistance to TKIs." (PMID 34830169, 2021). "However, there is only limited knowledge of their roles in biological processes and drug resistance in lung cancers with EGFR mutations." (PMID 33924522, 2021). "The purpose of this study was to investigate whether SB exhibited anticancer activity in EGFR TKI-resistant lung cancer cells and to explore the underlying mechanism." (PMID 34068421, 2021). "The T790M mutation of EGFR often induces lung cancer cells to acquire resistance to EGFR‐TKIs." (PMID 33931980, 2021). "Finally, we discuss the possibility of exosomes as novel biomarkers in early detection, diagnosis, assessment of prognosis, and prediction of therapeutic response in EGFR-mutated lung cancer." (PMID 33855679, 2021). "MET exon 14 skipping mutation occurs in approximately 3% of lung adenocarcinoma and 2.3% of other lung cancer subtypes and is mutually exclusive with other known driver gene mutations such as EGFR, KRAS, and HER2, suggesting its potential as a true oncogenic driver site." (PMID 34660325, 2021). "It is assumed that the EGFR mutations of primary lung cancer could forecast the prognosis of patients with bone metastasis and tumor response to TKI therapy." (PMID 34722241, 2021). "Combination of PFKL/MET inhibitors and EGFR TKIs could be a rational therapeutic approach for lung cancer patients with EGFR mutation." (PMID 34368128, 2021). "However, due to the small sample size, our results showed a certain deviation from these epidemiological data: In our study, EGFR mutations were detected in 36.4% of patients in the lung cancer cohort (40/110)." (PMID 33828971, 2021). "We have identified that significantly overexpressed LncRNA SOX2‐OT levels in human lung carcinomas are associated to poorer overall survival in lung cancer patients, with lower clinical response to oncological treatments (Cisplatin/Taxanes/EGFR‐TKIs), ranging from 1 to 11 months." (PMID 33433063, 2021). "Key examples include EGFR-T790M mutations and resistance to EGFR inhibitors in EGFR-mutant lung cancer, ESR1 mutations in estrogen receptor positive breast cancer treated with endocrine therapy, and reversions of pathogenic mutations in BRCA1 and BRCA2 deficient cancers treated with PARP inhibitors." (PMID 34680271, 2021). "High abundance of EGFR and large internal deletions are frequently observed in brain tumors, whereas point mutations and small insertions within the kinase domain are common in lung cancer." (PMID 34206026, 2021). "Therefore, this study assessed the effectiveness of afatinib, erlotinib, and gefitinib in terms of OS (overall survival) and progression‐free survival (PFS) in EGFR mutation‐positive advanced non‐small cell lung cancer (NSCLC) patients." (PMID 33336895, 2021). "Our study revealed a unique EGFR germline mutation profile in Chinese patients with lung cancer." (PMID 34869019, 2021). "This review focuses on exosomes from lung cancer with a focus on EGFR mutations." (PMID 33855679, 2021). "We, therefore, hypothesized that dacomitinib and osimertinib combination therapy might be an effective first-line treatment for patients with advanced EGFR-mutant lung cancers by preventing the spectrum of acquired EGFR mutations observed." (PMID 34140482, 2021). "EGFR mutations are the most common molecular aberration found in lung cancers." (PMID 33572269, 2021). "We used four different approaches to detect mutations among the 50 patients with advanced EGFR-mutant lung cancer who acquired resistance to EGFR-TKIs, including ddPCR and NGS assays performed in plasma samples and NGS and Cobas assays performed in tissue samples." (PMID 33718183, 2021). "Our findings suggest that the detection of EGFR mutations in ctDNA samples from patient plasma may be a valuable, minimally invasive method for evaluating lung cancer." (PMID 34574036, 2021).
lung cancer (continued). "The detection of such common variants provides an alternative to sequencing of the tumor tissue in contexts in which the prevalence of these variants is frequent, such as the detection of KRAS mutations in colorectal cancers and Epidermal Growth Factor Receptor (EGFR)mutations in lung cancer." (PMID 33809567, 2021). "ALK and EGFR mutations coincide at a relatively low frequency in lung cancer patients." (PMID 34654390, 2021). "However, the role of PHLPP in resistance to EGFR-TKI in EGFR-mutation lung cancer remains undefined." (PMID 34168988, 2021). "Finally, based on the newest update of the Graded Prognostic Assessment for lung cancer using molecular markers (Lung-molGPA), the EGFR and anaplastic lymphoma kinase mutation status were included as prognostic factors for patients with NSCLC and BMs." (PMID 34439186, 2021). "Furthermore, EGFR mutant tumors respond poorly to immune checkpoint inhibitors; this is attributed to factors such as lower tumor mutation burdens in EGFR mutant lung cancer, but this remains poorly understood." (PMID 34944063, 2021). "In our institute, the CDx test for EGFR‐TKIs was changed from the Therascreen test (Therascreen) to the Cobas EGFR v2 test (Cobas) because only Cobas was approved for the use of osimertinib in patients with EGFR‐mutated non‐small cell lung cancer (NSCLC) with T790M mutations." (PMID 33528892, 2021). "At the same time, lung cancer patients with EGFR mutations have a 50–70% risk of brain metastases." (PMID 33435596, 2021). "Therefore, further studies should focus on TAS‐116 as a promising therapeutic option for EGFR‐mutated lung cancer." (PMID 33471376, 2021). "For example, in EGFR-mutant lung cancers, the point mutation leading to a substitution of methionine for threonine at amino acid position 790 in exon 20 of EGFR, known as the EGFR T790M gatekeeper mutation, is a leading cause of resistance to first- and second-generation EGFR inhibitors." (PMID 34071428, 2021). "EGFR mutations can affect the outcome of EGFR TKIs in lung cancer patients." (PMID 33448107, 2021). "For instance, two randomised Phase III trials suggest that afatinib failed to prolong patient life in the whole tested population of EGFR-mutant advanced lung cancer, however, afatinib significantly extended survival by 3 months to a specific EGFR-mutated subgroup compared to chemotherapy." (PMID 33430223, 2021). "The association between ANXA1 and EGFR in lung cancer cells was observed in our study, and our study results may provide another mechanism in which ANXA1 promotes the metastasis of lung cancer cells through the modulation of the EGFR pathway." (PMID 34439260, 2021). "Although EGFR-mutated lung cancers showed greater activation profiles (p < 0.001), the wild-type tumors also had a high variation that could not be explained by the tumor's intrinsic properties." (PMID 33748471, 2021). "Therefore, with regard to TF modulation, future studies should also focus on lung cancer cells with mutated, overactive EGFR." (PMID 34205482, 2021). "Shlomi et al2 also reported that volatile organic compounds in exhaled breath could discriminate patients with lung cancer with EGFR variant from those harboring wild-type EGFR with an accuracy of 83%." (PMID 33783517, 2021). "Outside of EGFR TKIs, the bi-specific EGFR antibody amivantamab-vmjw has shown some preclinical activity against multiple EGFR mutated lung cancer models and was also approved for use in advanced EGFR exon 20 insertion mutated lung cancer." (PMID 34944068, 2021). "This study aimed to examine EGFR mutations of primary lung adenocarcinoma in sputum samples using droplet digital polymerase chain reaction (ddPCR) and compare it with an EGFR mutation in surgically resected lung cancer." (PMID 33757469, 2021).
lung cancer (continued). "Lung cancer has been reported to cause the highest number of BM cases with an incidence rate of 9–46%, depending on histological type, Epidermal Growth Factor Receptor (EGFR) mutation status, and disease stage." (PMID 33807384, 2021). "There are some known lung cancer biomarkers such as epidermal growth factor receptor (EGFR) mutations, anaplastic lymphoma kinase, ROS gene rearrangements or immunohistochemical expression of programmed death-ligand 1 (PD-L1) that significantly influenced clinical practice." (PMID 34501309, 2021). "Although preclinical models demonstrate that uncommon mutations respond to EGFR‐TKIs to some extent, the clinical effectiveness of EGFR‐TKIs in non‐small cell lung cancer (NSCLC) patients with these uncommon mutations remains unclear." (PMID 33124128, 2021). "Improved understanding of the biology of lung cancer has resulted in the development of new biomarker-directed therapies targeting molecular alterations (eg, EGFR mutations, ALK rearrangements, ROS1 rearrangements, and BRAF V600E mutations), which have prolonged survival of lung cancer patients." (PMID 33442422, 2021). "Activation of MAPK signaling via BRAF mutations may limit the activity of EGFR inhibitors in EGFR-mutant lung cancer patients." (PMID 34921211, 2021). "Osimertinib was approved as a first‐line treatment for lung cancer with EGFR mutations in 2018, and therefore tarloxotinib may be a suitable second‐line EGFR‐TKI for lung cancers with exon 19 deletions or with L858R point mutation." (PMID 33710795, 2021). "A cross‐platform comparison including 38 samples from patients with EGFR‐mutated lung cancer from the phase 1 AURA trial analyzed the concordance between the results obtained with BEAMing, ddPCR, Therascreen, and cobas®EGFR Mutation Test using tissue results as a nonreference standard." (PMID 33107189, 2021). "Therefore, afatinib is a promising EGFR TKI for the management of patients with lung cancer with EGFR mutations." (PMID 33941115, 2021). "Thus, there was a clear inverse association between NE differentiation and EGFR expression in lung cancer." (PMID 34121659, 2021). "Given that patients with lung cancer with EGFR mutations exhibit unfavorable anti-PD-1 responses, regulation of cooperation among these lymphocyte subsets may be important for antitumor immunity in lung tumors." (PMID 34663810, 2021). "Therefore, the distribution and prevalence of EGFR germline variants and their roles in lung cancer genetic predisposition in Chinese population remain to be elucidated." (PMID 34869019, 2021). "NGS tests may increase the identification of patients with lung cancer due to the K860I single mutation, and it is therefore necessary to collect and report cases to examine the appropriate selection of EGFR‐TKIs." (PMID 33942527, 2021). "Also, lung cancer cell expressing mutated EGFR is associated with decreased immune cell infiltration and T-cell mediated antitumor immunity." (PMID 34239594, 2021). "This indicates the role of EGFR mutations in suppressing TRAIL expression in lung cancer." (PMID 34282054, 2021). "Regulating the downstream signaling pathways of EGFR may act as important mechanisms underlying the cooling-heat medicine in exerting anticancer function in lung cancer." (PMID 34646330, 2021). "This is because the included patients for this study were the advanced or metastatic EGFR mutation-positive NSCLC patients enrolled in the public health insurance in Fuzhou city who used the expensive novel anti-lung cancer medicine newly covered by the insurance." (PMID 34992534, 2021). "Lung cancer continues to be the leading cause of cancer death, with 20–25% of deaths occurring in non-smoking patients, these usually being the cases with mutations in driver genes such as the Epidermal Growth Factor Receptor (EGFR)." (PMID 34465283, 2021).